FGFRL1 (fibroblast growth factor receptor like 1)
Diseases named in the same sentence as FGFRL1 in open-access papers (continued):
Sharing a sentence is not in itself a finding about the gene and the disease.
colorectal cancer (3 papers, 2014 to 2020). A primary or metastatic malignant neoplasm that affects the colon or rectum. "Three cell lines carry frameshift mutations and the remaining cell line carries a non-synonymous point mutation with a predicted damaging effect, indicating a loss of function of the FGFRL1 protein in colorectal cancer." (PMID 25193853, 2014). "Different FGFR specific inhibitors are currently under development, and further evaluation of their activity in the subset of colorectal cancer with FGFR/FGFRL1 alterations should be pursued." (PMID 25193853, 2014). "FGFRL1 thus acts as a negative regulator of FGFR1 signaling and loss of function mutations described here may represent a novel mechanism of FGF signaling activation in colorectal cancer." (PMID 25193853, 2014).
esophageal cancer (3 papers, 2025 to 2026). A primary or metastatic malignant neoplasm involving the esophagus. "FGFRL1, one of the least explored FGFRs, has recently been shown to have implications in cancer, but its functional significance in esophageal cancer (EC) remains largely unexplored." (PMID 41481426, 2026).
non-small cell lung carcinoma (3 papers, 2020 to 2022). A group of at least three distinct histological types of lung cancer, including non-small cell squamous cell carcinoma, adenocarcinoma, and large cell carcinoma. "From all above, we can draw the conclusion that lncRNA FGD5-AS1 promotes non-small cell lung cancer cell proliferation through sponging hsa-miR-107 to up-regulate FGFRL1." (PMID 31919528, 2020). "Thence, we concluded that lncRNA FGD5-AS1 promotes non-small cell lung cancer cell proliferation through sponging hsa-miR-107 to up-regulate FGFRL1." (PMID 31919528, 2020). "LncRNA FGD5-AS1 promotes non-small cell lung cancer cell proliferation through sponging hsa-miR-107 to up-regulate FGFRL1." (PMID 31919528, 2020). "In the present study, we aimed to indicate that FGD5-AS1 may promote non-small cell lung cancer cell proliferation through sponging hsa-miR-107 to up-regulate FGFRL1." (PMID 31919528, 2020). "Besides, FGD5-AS1 could accelerate non-small cell lung cancer (NSCLC) cell proliferative capability by regulating miR-107/FGFRL1 axis." (PMID 35761386, 2022).
small cell lung carcinoma (3 papers, 2023 to 2025). Small cell lung cancer (SCLC) is a highly aggressive malignant neoplasm, accounting for 10-15% of lung cancer cases, characterized byrapid growth, and early metastasis. "The results of clinical sample detection show that FGFRL1 is overexpressed in small-cell lung cancer (SCLC) tissues, and high FGFRL1 expression is associated with the clinical stage, chemotherapy response, and survival time of SCLC patients." (PMID 40699684, 2025). "For instance, in small cell lung cancer, enhanced FGFRL1 interacts with alpha‐enolase to activate its downstream PI3K/AKT pathway, leading to chemotherapy resistance." (PMID 37750089, 2023).
bladder tumors (2 papers, 2014 to 2020). "Recurrent (>10%) FGFRL1 somatic mutations were also reported in bladder tumors." (PMID 25193853, 2014). "Recently, Yang et al41 reported that miR‐210‐3p inhibited bladder tumour growth and metastasis by targeting FGFRL1." (PMID 32396269, 2020).
breast carcinoma (2 papers, 2013 to 2022). "An interesting possibility is that FGFRL1 could also in the nucleus act via FGFR1, which has been reported to have nuclear functions in breast cancer." (PMID 35053442, 2022). "Further, this miRNA modulates the mitochondrial functioning and metabolism, represses FGFRL1 and E2F3 expression, which inhibits cell apoptosis in hypoxia response, predicts poor survival in patients with breast cancer and activates notch signalling pathway in angiogenesis." (PMID 23387986, 2013).
gastric cancer (2 papers, 2018 to 2020). A primary or metastatic malignant neoplasm involving the stomach. "This was consistent with the findings in this study that elevated FGFRL1 was an indicator for the poor prognosis in gastric carcinomas." (PMID 29675438, 2018).
osteosarcoma (2 papers, 2020 to 2025). A usually aggressive malignant bone-forming mesenchymal neoplasm, predominantly affecting adolescents and young adults. "The results of trans-well assays show that miR-210 promotes osteosarcoma cell migration and invasion, while FGFRL1 overexpression deprives the promotion effect of miR-210 on cell migration and invasion." (PMID 40699684, 2025). "However, in some types of cancer, such as osteosarcoma and pancreatic cancer, FGFRL1 appears to inhibit the progression and invasion of cancer." (PMID 40699684, 2025). "Indeed, Liu et al37 demonstrated that, in osteosarcoma cells, miR‐210 promoted cell migration and invasion by targeting FGFRL1." (PMID 32396269, 2020). "When overexpressed in MG-63 osteosarcoma cells, FGFRL1 showed a negative effect on cell proliferation." (PMID 40699684, 2025).
pancreatic cancer (2 papers, 2025). "Therefore, it seems like FGFRL1 downregulation promotes the progression and chemoresistance of pancreatic cancer by promoting M2 polarization of macrophages." (PMID 40699684, 2025).
Wolf-Hirschhorn syndrome (2 papers, 2014 to 2022). Wolf-Hirschhorn syndrome (WHS) is a developmental disorder characterized by typical craniofacial features, prenatal and postnatal growth impairment, intellectual disability, severe delayed psychomotor development, seizures, and hypotonia. "This deletion is distal to the Wolf-Hirschhorn syndrome critical regions, but includes the FGFRL1 gene proposed to be a plausible candidate for part of the craniofacial characteristics of Wolf-Hirschhorn syndrome patients." (PMID 25506393, 2014). "Also, deletion of the Fgfrl1 gene in a mouse model resulted in Wolf-Hirschhorn syndrome (WHS), including skeletal anomalies and congenital heart defects." (PMID 35980984, 2022).
aneurysm (1 paper, 2021). Bulging or ballooning in an area of an artery secondary to arterial wall weakening. "Besides, Fibroblast Growth Factor Receptor-Like 1 (FGFRL1) and Pleckstrin Homology and FYVE Domain Containing 2 (PLEKHF2) may affect the transportation of intracellular substances to promote aneurysm formation, through the hsa_circ_0005073/hsa_circ_0081968/hsa-miR-107 regulated axis." (PMID 34777635, 2021).
colon cancer (1 paper, 2023). "For example, changes in FGFRL1 gene can promote the occurrence and progression of colon cancer." (PMID 36755247, 2023).
congenital diaphragmatic hernia (1 paper, 2025). A posterolateral defect of the diaphragm that allows passage of abdominal viscera into the thorax, leading to respiratory insufficiency and persistent pulmonary hypertension with high mortality. "In addition, congenital diaphragmatic hernia (CDH), familial gastroschisis, and congenital heart disease are also demonstrated to be associated with FGFRL1 mutation or variation." (PMID 40699684, 2025). "In a nitrofen model of congenital diaphragmatic hernia (CDH), decreased expression of FGFRL1 was detected during the later gestational stages of the mice." (PMID 40699684, 2025).
esophageal tumors (1 paper, 2014). "This fact raises doubts about several recent reports, which detected FgfrL1 protein with polyclonal antibodies in mouse kidney, rat diaphragm, epithelium of human bladder and stroma of esophageal tumors." (PMID 25126760, 2014).
hepatocellular carcinoma (1 paper, 2020). A malignant tumor that arises from hepatocytes. "In a study of hepatocellular carcinoma, Yang et al38 found that miR‐210 promoted cancer angiogenesis by targeting FGFRL1." (PMID 32396269, 2020).
larynx carcinoma (1 paper, 2025). A primary or metastatic malignant neoplasm involving the larynx. "miR-210 is a main downstream effector gene of HIF-1, which is upregulated in several types of solid tumors It was found that the FGFRL1 protein level decreased when miR-210 was overexpressed in larynx carcinoma cell line SCC10A." (PMID 40699684, 2025).
lung tumors (1 paper, 2018). "Furthermore, expression levels of the downstream markers of the corresponding microRNAs, namely PTEN, MARCKs, TPM-1, PDCD4, SPRY-2, ETS-1, ZEB-2, FGFRL-1, EFNA-3, and k-RAS were downregulated in the lung tumor lesions of patients with the underlying condition compared to non-COPD patients." (PMID 29371906, 2018). "Levels of markers regulated by histone acetylation such as PTEN, MARCKs, EGFL-7 (almost significant decrease), FGFRL-1, SNAIL-1, P63, and k-RAS were significantly reduced in the lung tumors compared to non-tumors only in patients with LC-COPD." (PMID 29371906, 2018).
renal dysplasia (1 paper, 2012). Renal dysplasia is a form of renal malformation in which the kidney(s) are present but their development is abnormal and incomplete. "In sharp contrast, Fgfrl1 null mice have a phenotype with renal dysplasia very similar to mice with a conditional disruption of Fgf8 or a compound disruption of the two receptors Fgfr1 and Fgfr2." (PMID 22432025, 2012).
respiratory failure (1 paper, 2009). The significant impairment of gas exchange within the lungs resulting in hypoxia, hypercarbia, or both, to the extent that organ tissue perfusion is severely compromised. "In contrast, knock-out (KO) of FGFRL1 in mouse, as first described by Baertschi and collaborators, caused animals to die early after birth due to respiratory failure associated with diaphragm alteration." (PMID 19740411, 2009).
squamous cell carcinoma (1 paper, 2025). A carcinoma arising from squamous epithelial cells. "The hematoxylin and eosin staining showed that FGFRL1-deficient cells formed well-differentiated squamous cell carcinomas in vivo, whereas wild-type cells formed moderately differentiated squamous cell carcinomas." (PMID 40699684, 2025).
tumor (22 papers, 2010 to 2025). "It was found that FGFRL1 was positively associated with lymph node metastasis and tumor growth in the patients." (PMID 40699684, 2025). "Microarray analysis of mRNA expression revealed that FGFRL1 depletion resulted in a decreased expression of proteins associated with motility and an invasion of tumor cells." (PMID 40699684, 2025). "FGFRL1 deficiency, however, reduced tumor cell motility in vitro and decreased tumor growth in a xenograft model of esophageal squamous cell carcinoma." (PMID 37109525, 2023). "Transcriptomics of FGFRL1-KD cells and xenografts revealed major changes in genes regulating differentiation, ECM turnover, and tumor–stromal interactions associated with decreased growth in FGFRL1-KD xenografts." (PMID 35053442, 2022). "Loss of function of FGFRL1 significantly influenced cell proliferation, apoptosis, and migration of OC cells in vitro and tumor growth in vivo." (PMID 29675438, 2018). "EMT also seems to be linked with the function of miR-205-5p, while miR-210-3p seems to inhibit the tumor growth and metastasis of BC via targeting fibroblast growth factor receptor-like 1 and is also strongly associated with markers of tumor hypoxia like HIF-1α, CA9, Glut-1 protein." (PMID 35365098, 2022). "For example, CSC-Exos carrying miR-210-3p target the regulation of FGFRL1, potentially acting as a tumor suppressor." (PMID 39200273, 2024). "miR-210 has been shown to induce tumor angiogenesis in HCC by activation of fibroblast growth factor receptor-like 1 (FGFRL1)." (PMID 37507808, 2023). "FGFRL1 knockdown significantly decreased the tumour volumes after treatment with PBS or drugs; in contrast, the tumour volume of the FGFRL1 overexpression group was significantly increased compared with the corresponding control group." (PMID 31957179, 2020). "It is up-regulated in hypoxia-related activation of HIF1α, is a key factor in induction of (tumor) cell proliferation by targeting fibroblast growth factor receptor-like 1 (FGFRL1) and modulates mitochondrial alterations due to hypoxia." (PMID 31652839, 2019). "FGFRL1 significantly promoted cell proliferation and migration of OC cells in vitro and tumor growth in vivo." (PMID 29675438, 2018). "In high-grade serous ovarian tumor, FGFRL1 mRNA isoform was identified with tumor-specific expression." (PMID 29675438, 2018). "In the current study, FGFRL1 was highly expressed in OC tissues and other different neoplastic diseases." (PMID 29675438, 2018). "In vitro cell proliferation, apoptosis and migration assays, and in vivo subcutaneous xenograft tumor models were used to determine the role of FGFRL1." (PMID 29675438, 2018). "This study identified an inverse correlation between tumor size and miR-210 expression level, and found that rescue with exogenous FGFRL1 was sufficient to promote tumor growth in the miR-210 expressing cells." (PMID 25809609, 2015). "The weight and size of tumors formed by FGFRL1-siRNA transfected cells are significantly decreased in comparison with the tumors formed by the siRNA–control transfected cells in a nude mice transplant tumor model." (PMID 40699684, 2025). "Altered internalization and defective trafficking of membranous FGFRL1 in tumor cells could also lead to the observed localization of FGFRL1 in nuclei or cytoplasm." (PMID 35053442, 2022). "Transfection efficiency of FGFRL1 in tumour xenografts was detected by qRT‐PCR and Western blot." (PMID 31957179, 2020). "Taken together, this study provides valuable insight into FGFRL1, which plays an important role in tumor growth and Hh signaling which could serve as potential therapeutic targets for the treatment of OC." (PMID 29675438, 2018). "FGFRL1 promoted tumor progression by crosstalk with Hedgehog (Hh) signaling." (PMID 29675438, 2018). "Taken together, FGFRL1 is a potential predictor and plays an important role in tumor growth and Hh signaling which could serve as potential therapeutic targets for the treatment of OC." (PMID 29675438, 2018).
tumor (continued). "FGFRL1 tumor suppression function was also observed in vivo through experiments in which cells stably expressing miR-210 were subcutaneously transplanted into nude mice, resulting in significantly reduced tumor growth." (PMID 25809609, 2015). "While this work was in preparation, three new miR-210 targets were validated, i.e. HOXA1, HOXA9 and FGFRL1, and the analysis of tumour xenografts derived from cancer cell lines overexpressing miR-210 suggested a potential involvement of miR-210 in tumour growth initiation." (PMID 20436681, 2010). "FGFRL1 could accelerate tumor growth in different neoplastic diseases." (PMID 29675438, 2018). "Our data show that FGFRL1 is expressed in macrophages, and FGF2 has been shown to regulate programming of TAM and to control tumor growth and antitumor immunity." (PMID 38358826, 2024). "The comparison of differentially expressed genes, specifically in FGFRL1-KD xenografts versus controls, revealed high-ranking upregulated genes such as BMP7 and TIMP3, with specific activities related to tumor–stromal interactions and tumor suppression." (PMID 35053442, 2022). "When FGFRL1-KD PC3M cells were implanted into nude mice, the tumor take rate markedly decreased, and the formation of xenografts was considerably slower than that of control cells." (PMID 35053442, 2022). "Besides having a membrane localization-associated decoy function, which could primarily function in normal cells and tissues, FGFRL1 may, in a tumor tissue context, contribute to PCa progression by other modes of action, such as an FGF-binding-dependent co-receptor function via FGFR1." (PMID 35053442, 2022). "Tumor expression of miR-210 significantly increased in LC-COPD compared to LC patients, while that of its downstream targets FGFRL-1 and EFNA-3 was reduced in the former patients." (PMID 29371906, 2018). "In these patients, tumor expression of miR-126 and miR-451 and that of the biomarkers PTEN, MARCKs, FGFRL-1, SNAIL-1, P63, and k-RAS were reduced." (PMID 29371906, 2018). "The large majority of super enhancers were tumor-specific and enriched for tumor-related genes, such as PAX6, FGFRL1, FGFR1, SKI, and BOC." (PMID 30279357, 2018). "Our bioinformatics analyses strongly suggested that FGFRL1 functions primarily relate to tissue morphogenesis, differentiation, and modulation of the ECM and the regulation of tumor–stroma interactions that affect tumor growth, which are all hallmarks of FGF/FGFR functions." (PMID 35053442, 2022). "Because FGFRL1 xenograft growth was strongly inhibited, the CASTIN analysis tool was used to identify significantly enriched tumor–stroma interactions between receptors and cognate ligands, expressed specifically by mouse cells (stromal cells) and human tumor cells (PC3M cells)." (PMID 35053442, 2022). "FGFRL1-KD, via increasing PTX3, could thus strongly affect cellular functions, tumor growth, and vascularization." (PMID 35053442, 2022).